GCGR (glucagon receptor)
Diseases named in the same sentence as GCGR in open-access papers (continued):
Sharing a sentence is not in itself a finding about the gene and the disease.
Hepatic steatosis (10 papers, 2017 to 2026). Steatosis is a term used to denote lipid accumulation within hepatocytes. "Weight reduction, anorexigenic and hypoglycaemic effects have been linked to GLP1 activation, while GCGR activation is thought to contribute primarily to hepatic steatosis attenuation and improved mitochondrial respiration." (PMID 35203484, 2022). "Based on our present study, we uncover an essential role of CD9 in counteracting hepatic steatosis, and highlight it as a mediator of the hepatic effects of GCGR agonist." (PMID 38837628, 2024). "Glucagon receptor (GCGR) agonism offers potentially greater effects on the mitigation of hepatic steatosis." (PMID 38837628, 2024). "Hepatic steatosis and certain diets have been related to decreased hepatic GCGR expression in animals, probably due to GCGR internalization." (PMID 37635984, 2023). "Finally, perhaps someone with fatty liver disease would benefit more from a GLP‐1R/GCGR co‐agonist than an agent targeting GIPR, if equally efficacious for weight loss." (PMID 41287212, 2026). "CD9 medicates the hepatic beneficial effects of GCGR signaling, and may server as a promising therapeutic target for hepatic steatosis." (PMID 38837628, 2024). "Additionally, our study highlights CD9 as a mediator of GCGR agonist's hepatic benefits, and may server as a promising therapeutic target for liver steatosis." (PMID 38837628, 2024). "Thus, CD9 medicates the hepatic beneficial effects of GCGR signaling, and may server as a promising therapeutic target for hepatic steatosis." (PMID 38837628, 2024). "Finally, a novel triple GLP1R/GCGR/GIPR agonist, HM15211, induced significant reductions in liver steatosis, fibrosis, and inflammation in mice; a phase 2 clinical trial is ongoing (NCT04505436)." (PMID 35203484, 2022). "Further, that the absence of glucagon receptor made mice resistant to diet-induced weight gain and hepatic steatosis." (PMID 29065174, 2017).
type 1 diabetes (10 papers, 2021 to 2025). "The therapeutic potential of inhibition of glucagon’s action in type 1 diabetes has been extensively investigated, and a phase II trial to examine the effects of the glucagon receptor antagonist volagidemab was reported recently." (PMID 40166445, 2025). "These beneficial effects were also present when a GCGR antagonist was combined with basal and prandial insulin treatment in type 1 diabetes patients." (PMID 36404376, 2023). "Several studies in animal models have shown that type 1 diabetes was attenuated by treating the animal with GCGR antagonists or genetic deletion of the GCGR." (PMID 37586587, 2023). "Glucagon receptor antagonists are in clinical trials as a treatment to lower blood glucose in patients with both type 2 and type 1 diabetes." (PMID 36002172, 2022). "Thus, further exploration into the potential role of WAT glucagon receptor signaling in type 1 diabetes is required to understand the potential impact of the use of glucagon receptor antagonists in this patient population." (PMID 36002172, 2022). "Our study evaluated the effects of liraglutide, GCGR mAb monotherapy, and combined strategy in glucose control and islet β-cell regeneration and provided useful clues for the future clinical application in type 1 diabetes." (PMID 39280767, 2021).
metabolic dysfunction-associated steatohepatitis (9 papers, 2022 to 2026). Metabolic dysfunction-associated steatohepatitis (MASH, formerly known as nonalcoholic steatohepatitis or NASH) is a type of fatty liver disease. "Survodutide, a novel GLP-1/glucagon receptor co-agonist, is currently undergoing clinical evaluation for its therapeutic potential in metabolic dysfunction-associated steatohepatitis (MASH)." (PMID 41001122, 2025). "Under research, there is also pemvidutide (ALT-801), another GLP-1/glucagon receptor dual agonist, which has been tested primarily in a mouse model of metabolic dysfunction-associated steatohepatitis (MASH)." (PMID 39125772, 2024).
liver fibrosis (8 papers, 2022 to 2025). "This is supported by the recent report on the resolution of NASH and hepatic fibrosis by cotadutide and the underlying mechanistic contribution of GCGR agonism." (PMID 36356832, 2022). "All studies showed the superiority of dual GIP/GLP-1RA, GCGR/GLP-1RA or GLP-1RA to reverse the liver fibrosis degree by at least one stage in individuals with MASLD and T2D." (PMID 41246119, 2025). "Previous metabolomic and transcriptomic study of Cotadutide (GLP-1R/GCGR dual agonist) in hepatic fibrosis identified its effects on pathways related to lipogenesis, fibrosis, and inflammation." (PMID 40230860, 2025). "That study also demonstrated that a GLP-1R/GCGR dual agonist induced body weight loss across species, which is promising for ALT-801 development to treat NASH and the accompanying liver fibrosis." (PMID 35461369, 2022). "As expected, dual GIP/GLP-1RA, GCGR/GLP-1RA and GLP-1RA treatments significantly reversed liver fibrosis and reduced intrahepatic lipid percentage." (PMID 41246119, 2025). "Dual GIP/GLP-1RA, GCGR/GLP-1RA and GLP-1RA were significantly superior in reversing the liver fibrosis degree (OR 3.72; 95% CI: 2.72, 5.09; p<0.001) and decreasing the LFC (MD -18.90; 95% CI: -18.43, -19.37; p<0.001) compared with other active therapies or placebo." (PMID 41246119, 2025).
Mahvash disease (6 papers, 2011 to 2026). "Mahvash disease is a rare autosomal recessive condition caused by biallelic inactivating variants in the GCGR gene, impairing glucagon signaling and leading to alpha-cell hyperplasia and pancreatic neuroendocrine tumors (PNETs)." (PMID 41649336, 2026). "Mahvash disease, an autosomal recessive disorder caused by biallelic inactivating GCGR mutations, is rare but has been gradually recognized." (PMID 34002801, 2021). "Reactive ACH is the most frequent type, accounting for 42% of cases and results from defective glucagon receptor signaling, either due to inactivating mutations or deletions of the glucagon receptor gene or glucagon receptor intracellular pathways, also known as Mahvash disease." (PMID 39309109, 2024). "Chronic absence of glucagon signalling occurs in Mahvash disease, caused by a homozygous missense mutation in the GCGR, which leads to a 96% reduction in glucagon binding." (PMID 38579751, 2024). "Glucagon signalling deficiency syndromes, as exhibited by patients with Mahvash disease, GCGR−/− mice and pharmacological blockade of GCGR, are notable for very high plasma levels of glucagon and amino acids." (PMID 38579751, 2024). "We have recently described for the first time a patient with a novel disease (Mahvash disease) of marked hyperglucagonemia without glucagonoma symptoms, diffuse α cell hyperplasia, and PNETs associated with a homozygous inactivating GCGR mutation (P86S)." (PMID 21853126, 2011). "Hereditary, biallelic inactivating mutations of the GCGR gene is clinically characterized by hyperglucagonemia without glucagonoma, hyperaminoacidemia, transformation of hyperplastic islets into glucagon producing microadenomas and PNET, also known as Mahvash disease." (PMID 34002801, 2021). "Individuals with Mahvash disease have a phenotype very similar to that observed in mice lacking the glucagon receptor (GCGR−/−)." (PMID 38579751, 2024).
Glucose intolerance (5 papers, 2021 to 2024). Glucose intolerance (GI) can be defined as dysglycemia that comprises both prediabetes and diabetes. "Retratrutide (LY3437943), a novel triple GLP-1, GIP, and glucagon receptor agonist, has a greater insulinotropic effect from both GIP and GLP-1 receptors than the glucose intolerance induced by the glucagon receptor." (PMID 39061960, 2024). "Chronic GCGR agonism induces glucose intolerance, fitting this classical view; however, the role of glucagon in glucose metabolism is expanding." (PMID 33411693, 2021). "Additionally, we generated β-cell-specific GCGR knockout mice which glucose intolerance was more severe when fed a high-fat diet (HFD)." (PMID 34572144, 2021). "Conversely, others who have studied intra-islet GCGR signalling in germline or conditional β-cell knock out of the GCGR using a mouse insulin promoter (MIP)Cre-driven mechanism have not reported glucose intolerance." (PMID 38677509, 2024).
Insulin resistance (5 papers, 2013 to 2025). Increased resistance towards insulin, that is, diminished effectiveness of insulin in reducing blood glucose levels. "Our previous study demonstrated that reducing insulin resistance with a glucagon receptor antagonist improves cardiac diastolic function across different HFpEF models." (PMID 40521197, 2025). "Indeed, olanzapine-induced increases in blood glucose are ablated in glucagon receptor knockout mice, despite the onset of olanzapine-induced insulin resistance (as measured by an insulin tolerance test)." (PMID 31555747, 2019). "Furthermore, as antagonism of the glucagon receptor has been shown to improve islet function in mice with insulin resistance induced by a HFD, GSK706A could suggestively be combined with an inhibitor of glucagon action to achieve more potent glucose-lowering effects." (PMID 23781322, 2013). "Notably, GLP-1 receptor agonists, as well as dual GLP-1/GIP and GLP-1/glucagon receptor agonists, appear to exert the most comprehensive effects on MASLD, simultaneously improving steatosis, insulin resistance, inflammation, and body weight." (PMID 40650294, 2025).
non-alcoholic fatty liver disease (5 papers, 2021 to 2025). "G49 is another GLP-1R/GCGR dual agonist shown to improve liver regeneration in non-alcoholic fatty liver disease." (PMID 37091864, 2023). "However, for patients with complex metabolic needs, such as those at risk for non-alcoholic fatty liver disease (NAFLD) or dyslipidaemia, Retatrutide could be a valuable option - especially as future long-term studies may reveal additional benefits from glucagon receptor activation." (PMID 40471293, 2025). "Efficacy of BI456906 as a treatment for non-alcoholic steatohepatitis (NASH), the most severe form of non-alcoholic fatty liver disease (NAFLD), is also expected, due to the emerging successful approach for this pathology using dual GLP-1R/GCGR agonists." (PMID 34195230, 2021).
steatosis (5 papers, 2024 to 2025). Increased lipid within the cytoplasm of cells. "Female glucagon receptor knockout mice are prone to steatosis when fed a MASH‐promoting GAN diet and a high fat diet." (PMID 39985139, 2025). "Our results suggest that permanent genetic deletion of the glucagon receptor may result in steatosis and hypercholesterolemia and thus highlight glucagon as an important physiological regulator of not just glucose, but also hepatic lipid metabolism." (PMID 39985139, 2025). "GCGR/GLP-1R dual agonism is also a focus in the treatment of NASH as it can potentially ameliorate hepatic fat accumulation, steatosis and fibrosis, alongside reductions in bodyweight." (PMID 38095657, 2024).
hepatoma (4 papers, 2020 to 2024). "Hepatoma cells are convenient for testing proximal GCGR signalling events such as cAMP and PKA activation, but are not suitable for modelling downstream metabolic responses such as glucose output or β-oxidation." (PMID 35718339, 2022). "We first examined the impact of pharmacological modulation of cellular cholesterol levels on GCGR signalling in Huh7 hepatoma cells." (PMID 35718339, 2022). "The interaction of RAMP2 with GCGR has functional consequences: here, we demonstrate that up-regulation of RAMP2 acutely increases agonist-stimulated cAMP production in hepatoma cells, a phenomenon that has previously been shown in other non-hepatocyte cell lines." (PMID 34271220, 2021). "Subcellular localisation of GCGR in the presence and absence of RAMP2 was investigated using confocal microscopy, trafficking and radioligand binding assays in human embryonic kidney (HEK293T) and human hepatoma (Huh7) cells." (PMID 34271220, 2021).
liver disease (4 papers, 2023 to 2025). "In subjects with liver diseases, such as NAFLD, GCGR resistance may affect this liver–α cell axis, as reduced hepatic GCGR expression or impaired GCGR signaling leads to decreased urea production, which, in turn, leads to hyperaminoacidemia and subsequent compensatory hyperglucagonemia." (PMID 37764697, 2023).
myocardial infarction (4 papers, 2019 to 2025). Gross necrosis of the myocardium, as a result of interruption of the blood supply to the area, as in coronary thrombosis. "Animal experiments have shown that inhibiting GCGR signaling improves branched-chain amino acid metabolism, enhances cardiac function after myocardial infarction, and attenuates cardiac remodeling by modulating the TAK1/p38 MAPK and KLF15/BCATm pathways." (PMID 41458542, 2025). "Correspondingly, mice with cardiomyocyte-specific knockout of GCGR showed better survival and less cardiac remodeling after myocardial infarction." (PMID 41458542, 2025). "For instance, GCGR mAb treatment reduced the size of myocardial infarction, improved myocardial remodeling after coarctation of the aortic arch, and had a protective effect on cardiac function." (PMID 37596940, 2023). "GCGR mAb inhibited cardiac hypertrophy and fibrotic remodeling and attenuated contractile dysfunction in the mouse models of myocardial infarction or pressure overload." (PMID 37596940, 2023). "GCGR blockage can improve cardiac function following a myocardial infarction." (PMID 37596940, 2023). "GCGR mAb enhanced insulin signaling and branched chain amino acid catabolism but inhibited the signaling pathway target of rapamycin to improve cardiac function after myocardial infarction." (PMID 37596940, 2023). "GCGR antagonism following myocardial infarction has been shown to improve cardiovascular function." (PMID 36009454, 2022). "Another study demonstrated that the anti-GCGR antibody REMD 2.59 significantly improved cardiac function and tissue remodeling in mice with myocardial infarction." (PMID 41458542, 2025).
pancreatic neuroendocrine tumor (4 papers, 2011 to 2026). Pancreatic endocrine tumor, also known as pancreatic neuroendocrine tumor (PNET), describes a group of endocrine tumors originating in the pancreas that are usually indolent and benign, but may have the potential to be malignant. "Hyperplasia of α-cells under defective glucagon signaling is not unique to rodent models, and a human case carrying a homozygous glucagon receptor mutation has been reported to show α-cell hyperplasia and islet cell tumor." (PMID 23671715, 2013). "We have recently demonstrated that a patient with an inactivating glucagon receptor mutation (P86S) also exhibits hyperglucagonemia and pancreatic α cell hyperplasia but further develops pancreatic neuroendocrine tumors (PNETs)." (PMID 21853126, 2011). "Hyperplasia of α-cells has also been reported in humans and a patient harboring a homozygous GCGR mutation (P86S) has been identified, who showed hyperglucagonemia without the glucagonoma symptoms, diffuse α-cell hyperplasia, and pancreatic neuroendocrine tumors." (PMID 26192435, 2015).
Alzheimer disease (2 papers, 2022 to 2025). A progressive, neurodegenerative disease characterized by loss of function and death of nerve cells in several areas of the brain leading to loss of cognitive function such as memory and language. "Carriers of known or presumed GCGR LoF variants do not have an increased risk of all-cause dementia or Alzheimer's disease, but individuals with a cAMP LoF GCGR variant have lower cognitive function as evaluated by 1 population-scale cognitive test." (PMID 40271226, 2025). "Nevertheless, we found no additional risk of Alzheimer's disease with impaired GCGR signaling." (PMID 40271226, 2025).
Anorexia (2 papers, 2017 to 2021). Lack of desire to eat (loss of appetite). "Hypothalamic GCG activated GCGR to stimulate downstream PKA pathway in the hypothalamic ARC, as i.c.v. co-infusion of the GCGR antagonist des-His1-[Glu9] GCG amide or the PKA inhibitor H-89 negated the ability of central GCG to induce anorexia." (PMID 28223965, 2017).
Anxiety (2 papers, 2018). Intense feelings of nervousness, tension, or panic often arise in response to interpersonal stresses. "The high co-expression with Crhr1 and stimulatory nature of the glucagon receptor suggest that like NPY, glucagon is a signal for a negative energy balance that affects in parallel food intake and anxiety." (PMID 30210279, 2018).
fibrosis (2 papers, 2025). the formation of excess fibrous connective tissue in an organ or tissue in a reparative or reactive process. "As a momentary conclusion, survodutide, cotadutide, and efinopegdutide dual GLP-1R/GCGR co-agonists display potential benefits in MASH-related fibrosis and cirrhosis, while pemvidutide and mazdutide need more investigations in this area." (PMID 40004572, 2025).
Hypertension (2 papers, 2024 to 2025). The presence of chronic increased pressure in the systemic arterial system. "The GCGR G40S allele, which impairs β-arrestin-1 recruitment, is associated with T2D, hypertension, altered renal sodium handling, and increased central adiposity in men, highlighting that impaired GCGR signaling is detrimental despite its key role in promoting hepatic glucose production." (PMID 40271226, 2025).
insulinoma (2 papers, 2021 to 2025). "Therefore, 83.3% of insulinomas were positive for both the GCGR and GLP-1R." (PMID 40649254, 2025). "We used incretin-responsive rat insulinoma-derived INS-1 832/3 cells, in which we first confirmed expression of GLP-1R, GIPR, and GCGR by qPCR." (PMID 33268378, 2021).